ATP8A2 (ATPase phospholipid transporting 8A2)
Description:
Catalytic component of a P4-ATPase flippase complex which catalyzes the hydrolysis of ATP coupled to the transport of aminophospholipids from the outer to the inner leaflet of various membranes and ensures the maintenance of asymmetric distribution of phospholipids (By similarity). Able to translocate phosphatidylserine, but not phosphatidylcholine. Phospholipid translocation also seems to be implicated in vesicle formation and in uptake of lipid signaling molecules (By similarity). Reconstituted to liposomes, the ATP8A2:TMEM30A flippase complex predominantly transports phosphatidylserine (PS) and to a lesser extent phosphatidylethanolamine (PE) (By similarity). Phospholipid translocation is not associated with a countertransport of an inorganic ion or other charged substrate from the cytoplasmic side toward the exoplasm in connection with the phosphorylation from ATP (By similarity). ATP8A2:TMEM30A may be involved in regulation of neurite outgrowth (By similarity). Proposed to function in the generation and maintenance of phospholipid asymmetry in photoreceptor disk membranes and neuronal axon membranes (By similarity). May be involved in vesicle trafficking in neuronal cells (By similarity). Required for normal visual and auditory function; involved in photoreceptor and inner ear spiral ganglion cell survival (By similarity).
Synonyms: ATPIB; ML-1; ATP; CAMRQ4; IB
Tractability: Antibody: UniProt places it where antibodies can reach, with high confidence; its Gene Ontology location is reachable by antibodies, with high confidence; UniProt predicts a signal peptide or a membrane-spanning region; the Human Protein Atlas places it where antibodies can reach. PROTAC: ubiquitination databases record sites on it; its protein half-life has been measured.
Gene: Protein-coding gene on chromosome 13 (25,371,974 to 26,025,851, forward strand). Ensembl gene ENSG00000132932.
Subcellular location: Membrane; Golgi apparatus membrane; Endosome membrane; Cell membrane; Photoreceptor outer segment membrane; Photoreceptor inner segment membrane
Subcellular location (Human Protein Atlas): Plasma membrane; Acrosome; Annulus; Mid piece; Nucleoplasm
Pathways (Reactome):
Transport of small molecules: Ion transport by P-type ATPases
Gene Ontology:
Molecular function: protein binding; phosphatidylethanolamine flippase activity; phosphatidylserine flippase activity; aminophospholipid flippase activity; ATP binding; ATP hydrolysis activity; ATPase-coupled intramembrane lipid transporter activity; magnesium ion binding; nucleotide binding; phosphatidylserine floppase activity
Biological process: aminophospholipid translocation; negative regulation of cell population proliferation; neuron development; phospholipid translocation; detection of light stimulus involved in visual perception; inner ear morphogenesis; neurofilament cytoskeleton organization; phospholipid transport; positive regulation of neuron projection development; positive regulation of phospholipid translocation; response to auditory stimulus; retina layer formation
Cellular component: Golgi apparatus; phospholipid-translocating ATPase complex; plasma membrane; endosome membrane; trans-Golgi network; endomembrane system; endosome; Golgi membrane; membrane
Genetic constraint (gnomAD): Loss-of-function variants: 50 observed, 86.93 expected, observed/expected ratio (o/e) 0.58, 90% interval 0.46 to 0.73. The upper end of that interval is the gene's LOEUF score, 0.73, which puts it in group 2 of 6, group 1 being the genes least tolerant of losing a copy. Missense variants: 815 observed, 974.36 expected, observed/expected ratio (o/e) 0.84, 90% interval 0.79 to 0.89. Synonymous variants: 373 observed, 377.57 expected, observed/expected ratio (o/e) 0.99, 90% interval 0.91 to 1.08.
Gene-disease validity (ClinGen):
ClinGen rates the evidence that ATP8A2 causes each of these diseases.
cerebellar ataxia, intellectual disability, and dysequilibrium (autosomal recessive): Definitive. A non-progressive cerebellar disorder characterized by ataxia associated with an intellectual disability, delayed ambulation and cerebellar hypoplasia.
Homologues: Orthologues: chimpanzee ATP8A2 (100% identical), macaque ATP8A2 (99% identical), dog ATP8A2 (96% identical), rat Atp8a2 (95% identical), pig ATP8A2 (94% identical), rabbit ATP8A2 (93% identical), guinea pig ATP8A2 (92% identical), mouse Atp8a2 (91% identical), tropical clawed frog atp8a2 (79% identical), zebrafish atp8a2 (76% identical), Drosophila melanogaster CG31729 (24% identical), Caenorhabditis elegans tat-5 (24% identical), and 1 more. Paralogues in human: ATP8A1 (66% identical), ATP8B1 (40% identical), ATP8B2 (39% identical), ATP8B4 (39% identical), ATP8B3 (36% identical), ATP10D (35% identical), ATP10A (35% identical), ATP10B (34% identical), ATP11B (34% identical), ATP11A (33% identical), ATP11C (32% identical), ATP9B (26% identical), and 1 more.